RAD18 (RAD18 E3 ubiquitin protein ligase)
Diseases named in the same sentence as RAD18 in open-access papers (continued):
Sharing a sentence is not in itself a finding about the gene and the disease.
tumor (23 papers, 2016 to 2026). "MAGEA4-induced stabilization of RAD18 has been proposed to cause increased tolerance to DNA damage and replicative stress to drive tumour progression." (PMID 38448672, 2024). "To assess the molecular specificity of drug-induced tumor killing on OBSCs, we used a CRISPR-modified variant of the U373 tumor line harboring a single-gene knockout in RAD18." (PMID 37192626, 2023). "This study used a carcinogen (17, 12-dimethylbenz[a]anthracene or DMBA, a synthetic polycyclic aryl hydrocarbon) to induce skin tumorigenesis in experimental mice, then compared mutation patterns in clonal tumors from Rad18+/+ and Rad18−/− genetic backgrounds." (PMID 34663880, 2021). "Additionally, xenograft tumors generated by RAD18-deficient cells exhibited slower regrowth compared to control groups after cisplatin treatment, as indicated by lower tumor burden in RAD18-deficient group." (PMID 40016217, 2025). "Collectively, these results provide a potential mechanism underlying RAD18-induced tumor stemness maintenance, which could be driven by enhanced levels of YAP." (PMID 35413945, 2022). "Moreover, while COSMIC Signature 22 predominated the overall mutational portrait of Rad18+/+ tumor genomes, the relative contribution of this signature to the overall mutations of Rad18−/− tumors was reduced by ~50% and replaced by other signatures." (PMID 34663880, 2021). "Mechanistically, RAD18 promoted tumor proliferation, migration and immunosuppressive microenvironment remodeling by activating the AKT/mTOR/c-Myc axis and regulating TGF-β1/PD-L1 expression." (PMID 42115304, 2026). "RAD18 is an E3 ubiquitin ligase that is involved in error‐prone replication, which can lead to carcinogenesis and tumor progression." (PMID 39865406, 2025). "The RAD18-YAP-TGF-β loop is highlighted as a critical driver of tumor stemness in TNBC and is identified as a potential therapeutic target." (PMID 40281554, 2025). "In vivo, tumor growth was promoted by RAD18, and RAD18 increased the recruitment of M2-type macrophages in nude mice." (PMID 40281554, 2025). "Comparison of normal versus tumor tissue also indicated significantly higher RAD18 levels in tumor samples." (PMID 40016217, 2025). "This makes Rad18 an attractive tumour treatment target, as it is only expressed and functions in few normal somatic cells." (PMID 38528023, 2024). "We therefore monitored survival of the RDM and RDFM mice to quantitatively determine the impact of Rad18 on tumour formation." (PMID 38528023, 2024). "To analyse the impact of Rad18 on tumour formation, we crossed RD and RDF mice with Eμ–Myc mice, henceforth called RDM and RDFM mice." (PMID 38528023, 2024). "Knockdown of RAD18 in combination with doxorubicin significantly increased the anti-tumor activity of doxorubicin." (PMID 39062505, 2024). "RAD18 overexpression contributed to an increase in tumor volume in contrast to the control group, and the tumors derived from RAD18 overexpressed cells showed less sensitivity to IR radiation compared to tumors formed by control cells." (PMID 35426246, 2022). "Overall, this study highlights the potential regulatory pathways of RAD18-mediated tumor progression, thus improving RAD18-based prognosis prediction and anticancer therapy." (PMID 35413945, 2022). "For the purpose of examining the effect of high RAD18 expression on the tumor-promoting effects of TNBC cells in vivo, shNC/shRAD18 TNBC cells were subcutaneously injected into nude mice." (PMID 35413945, 2022). "The TGF-β-neutralizing antibody significantly attenuated the expression levels of RAD18 and stemness markers, as well as tumor sphere formation in MDA-MB-231 cells in the co-cultivation system." (PMID 35413945, 2022). "Reciprocally, TGF-β from TAMs activated RAD18 in TNBC to enhance tumor stemness, forming a positive feedback loop." (PMID 35413945, 2022). "Rad18−/− tumor genomes also harbored significantly increased numbers of indels when compared with Rad18+/+ genomes." (PMID 34663880, 2021).
tumor (continued). "The Rad18/PCNA PLA signals sometimes appeared as massive signal clusters (>50 signals per nuclei) in individual tumor cells." (PMID 32701997, 2020). "The patients with low expression of RAD18 showed evidently tumor regression on MRI compared to those with high expression, thus indicating that RAD18 expression level was negatively correlated with the nCRT effect (P < 0.05)." (PMID 31033216, 2019). "Additionally, bioinformatics analysis using TNMplot revealed elevated RAD18 expression across various tumor types, including OC." (PMID 40016217, 2025). "Accordingly, targeting Rad18 in tumours may aim at improved chemotherapy treatment outcomes, rather than direct growth suppression." (PMID 38528023, 2024). "We find no activation defects or survival differences between Rad18 WT mice and two different models of Rad18 deficient tumour mice." (PMID 38528023, 2024). "RAD18 silencing promotes macrophage transformation from a pro-tumor to an antitumor phenotype." (PMID 35413945, 2022). "Nude mice bearing tumor xenografts were used to determine whether RAD18 induced radioresistance in ESCC cells in vivo." (PMID 35426246, 2022). "Furthermore, a xenograft nude mouse model showed that silencing RAD18 significantly slowed tumor growth after irradiation or/and 5‐Fu in vivo." (PMID 31033216, 2019). "Deficiencies in Rad18, FANCD2, BRCA2, and Rad51 are all known to sensitize tumor cells to CPT." (PMID 26871286, 2016). "Besides, it was also found that TGF-β activates macrophages to adopt an M2-like tumor-associated phenotype, and reciprocally, RAD18 is further activated in TNBC cells by TGF-β released from these macrophages, thereby forming a positive feedback loop that enhances tumor stemness." (PMID 40281554, 2025). "Accordingly, multiple roles for Rad18 function in other tumours may be envisioned." (PMID 38528023, 2024). "Therefore, polarized M2-like TAMs in the tumor microenvironment may function as a feedback regulator enhancing RAD18 expression and TNBC stemness via TGF-β." (PMID 35413945, 2022). "Taken together, our data revealed that tumors holes in the DDT network, and especially in RAD6/RAD18 pathway, can indicate vulnerabilities that enlarge therapeutic windows, and offer unique opportunities to optimize tumor-specific intervention with drugs that impinge on tumor weakness." (PMID 29721165, 2018). "A further potential source of error regards the concentration of Rad18 as a key downstream effector, potentially discounting the influence of other pathways through which ADAR1 affects tumor biology." (PMID 40852728, 2025). "RAD18, an E3 ubiquitin ligase, is integral to the error-prone TLS repair mechanism, which can promote carcinogenesis and tumor progression." (PMID 40016217, 2025). "Finally, we analysed whether a Rad18-KO would affect the tumour phenotype." (PMID 38528023, 2024). "MAGEA4 interacts with the RING ubiquitin ligase RAD18 and activates trans-lesion DNA synthesis (TLS), potentially favouring tumour evolution." (PMID 38448672, 2024). "A concomitant decrease in YAP and CD44 expression with RAD18 inhibition was observed, confirming the close correlation between RAD18-induced Hippo-YAP pathway activation and tumor stemness maintenance." (PMID 35413945, 2022). "In the present research, ESCC cells were found to be more sensitive to radiation when RAD18 was suppressed; however, RAD18 overexpression resulted in a converse effect on ESCC cell lines and tumor xenografts." (PMID 35426246, 2022). "Of the TLS factors profiled, only RAD18 and MAD2L2 (REV7) were overexpressed in all three tumor types." (PMID 34663880, 2021). "It interacts with the RING-type ubiquitin ligase RAD18 and activates the DNA synthesis (TLS), which may facilitate tumor evolution." (PMID 40244296, 2025). "Neither sex nor the two different Rad18-KO Eμ–Myc mouse models exhibited any difference in tumour development as assessed by spleen weight." (PMID 38528023, 2024).
tumor (continued). "Using non-cocultivated MDA-MB-231 cells as references, the tumor sphere formation, RAD18 levels, and stemness-related protein levels in the shNC co-cultivation group increased." (PMID 35413945, 2022). "Silencing RAD18 in TNBC cells reduced the number and size of tumor spheres." (PMID 35413945, 2022). "Overall, these findings confirmed that RAD18 may activate the Hippo-YAP pathway, followed by an increased expression of YAP, especially in the nucleus, thus enhancing tumor stemness and proliferation in TNBC cells." (PMID 35413945, 2022). "Thus, a survey analysis of gene expression profiles in three tumor types using TCGA reveals ample evidence of imbalance in expression levels of TLS polymerases and their activators (e.g., RAD18)." (PMID 34663880, 2021). "Apparently, Rad18 does not affect tumour formation or progression in the Eμ–Myc model." (PMID 38528023, 2024). "Thus, we hypothesized that RAD18-induced YAP activation in TNBC regulates macrophage polarization, thereby inducing the M2-like phenotype and promoting tumor progression." (PMID 35413945, 2022). "Likewise, the extent of plasma cell tumour generation did not depend on Rad18 genotype." (PMID 38528023, 2024).
adenocarcinoma (2 papers, 2016 to 2024). A common cancer characterized by the presence of malignant glandular cells. "MAGEA4 is known to mediate stabilization of RAD18 through inhibiting its ubiquitin-dependent proteolysis and promoting trans-lesion synthesis in the adenocarcinoma cell line H1299." (PMID 38448672, 2024). "To identify new regulators of the TLS pathway we defined the RAD18 protein interaction network in H1299 adenocarcinoma cells using label-free affinity purification and shotgun mass spectrometry (APMS)." (PMID 27377895, 2016).
RAD18 also shares sentences with these, for which no sentence is quoted: infection (2 papers); non-small cell lung carcinoma (2); acute myeloid leukemia (1); Alzheimer disease (1); biliary tract cancer (1); breast tumors (1); cervical tumor (1); endometrial cancer (1); lymphoma (1); ovarian serous carcinoma (1); ovarian tumors (1); pancreatic tumors (1); polyposis (1); renal cell carcinoma (1); skin cutaneous melanoma (1); Thyroid Carcinoma (1); uterine corpus endometrial carcinoma (1).